SOST (sclerostin)
Diseases named in the same sentence as SOST in open-access papers (continued):
Sharing a sentence is not in itself a finding about the gene and the disease.
acromegaly (continued). "Getting all available data together, we may conclude that in the heterogenous cohorts of acromegaly patients in which sclerostin has been studied to date, sclerostin values are highly variable with unknown clinical significance of this variability." (PMID 34448099, 2022). "Two recently published cross-sectional studies investigated sclerostin levels in controlled acromegaly before, although with significantly smaller patient numbers (18 and 12 controlled patients, respectively), both reporting comparable serum sclerostin levels between patients and healthy controls." (PMID 34448099, 2022). "The main limitation of the study is the relatively small number of included acromegaly patients, probably resulting in a lack of power to detect a significant association between sclerostin levels and VFs." (PMID 34448099, 2022). "Therefore, the significance of sclerostin levels in acromegaly is still debated, and the impact of disease control on sclerostin is still unknown." (PMID 36362602, 2022). "The study aimed primarily at evaluating sclerostin, OPG, and RANK-L concentrations in patients at different stages of acromegaly activity." (PMID 39741885, 2024). "Most studies conducted on groups of patients with acromegaly have not confirmed a direct influence of the GH/IGF-1 axis on sclerostin concentration, however, both positive and negative relationships have been observed." (PMID 39741885, 2024). "Significantly lower sclerostin concentrations were found in patients with acromegaly in comparison with CG, regardless of used classification (AA, CTA, CA, CTA+CA, AA+CTA+CA vs CG: p < 0.001, respectively)." (PMID 39741885, 2024). "Interestingly, another study showed an inverse correlation between sclerostin and GH levels, suggesting that the observed decrease in Wnt antagonists’ levels (such as sclerostin) could represent a compensatory mechanism to counteract the increased bone frailty in active acromegaly." (PMID 36362602, 2022). "However, we assume that acromegaly activity and duration of biochemical remission are important determinants which altogether with other factors, including age, menopausal state, and hypopituitarism may explain the observed differences in sclerostin levels between the studies." (PMID 34448099, 2022). "In conclusion, we demonstrated that plasma sclerostin levels were lower in patients with long-term controlled acromegaly compared to healthy controls, but could not directly link sclerostin levels to bone turnover, BMD or VFs." (PMID 34448099, 2022). "Within controlled acromegaly patients, we could not detect a significant relationship between sclerostin levels and parameters reflecting GH/IGF-1 activity." (PMID 34448099, 2022). "Since studies on sclerostin values in acromegaly show highly variable results, sclerostin is not likely to be the most important factor in acromegalic osteopathy, but could be a reflection of osteocyte activity." (PMID 34448099, 2022). "Therefore, we compared sclerostin concentrations between well-controlled acromegaly patients and healthy controls, and assessed its relationship with bone mineral density (BMD), and VFs in acromegaly." (PMID 34448099, 2022).
bone cancer (3 papers, 2022 to 2024). A primary or metastatic malignant neoplasm affecting the bone or articular cartilage. "There is evidence that sclerostin is associated with the biology of bone metastases and primary bone tumors in several entities." (PMID 38247829, 2024). "Sclerostin is known to be involved in bone metabolism and there are preliminary reports of its involvement in bone tumors and bone metastasis." (PMID 38247829, 2024). "There is increasing evidence in the literature that sclerostin plays a key role in several Wnt-related musculoskeletal disorders, primary bone tumors of various entities, and the development of bone metastases." (PMID 38247829, 2024). "The application of anti-sclerostin antibodies is expected for the treatments of bone cancers." (PMID 35563281, 2022).
carotid atherosclerosis (3 papers, 2018 to 2021). A thickening and loss of elasticity of the walls of carotid arteries that occur with formation of atherosclerotic plaques. "Sclerostin is an independent risk factor for carotid atherosclerosis." (PMID 32458213, 2020). "Further, other studies assessed the impact of sclerostin levels on carotid atherosclerosis." (PMID 33800939, 2021).
depression (3 papers, 2015 to 2024). "First, six infusions of ketamine associated with increased the levels of leptin and OPG, and decreased the levels of OC, OPN, SOST, PTH and FGF23 in patients with depression, which occurred immediately the day after the last infusion (Day 13) and lasted for 2-week post-infusion (Day 26)." (PMID 38287453, 2024). "In this study, we found an increase in plasma levels of leptin and OPG, and a decrease in levels of OC, OPN, SOST, PTH and FGF23 after six ketamine infusions in adults with depression, indicating that ketamine may mediate a beneficial effect on BMD." (PMID 38287453, 2024).
fibrosis (3 papers, 2021 to 2024). the formation of excess fibrous connective tissue in an organ or tissue in a reparative or reactive process. "SOST functions by binding to LRP5/6 and inhibiting canonical WNT/β-catenin signaling, a prominent targeted pathway of interest in cardiac fibrosis, regeneration, and angiogenesis." (PMID 39430425, 2024).
hypothyroidism (3 papers, 2020 to 2023). Abnormally low levels of thyroid hormone. "Interestingly, mRNA expression of osteokines osteocalcin, sclerostin, and Rankl were altered in bone tissue of hypothyroid mice, but not mice treated with zoledronate, underlining a greater impact of hypothyroidism on osteoblast/osteocyte physiology than anti-resorptive treatment." (PMID 36143246, 2022). "On the contrary, patients with hypothyroidism had lower serum concentrations of sclerostin than the other groups." (PMID 33312059, 2020). "We found that patients with hypothyroidism had much lower serum sclerostin concentrations than control subjects (66.54±48.13 pg/mL vs 145.91±81.36 pg/mL) (Mann Whitney test, p=0.009)." (PMID 33312059, 2020).
inflammatory bowel disease (3 papers, 2013 to 2021). A spectrum of small and large bowel inflammatory diseases of unknown etiology. "We have previously shown that treatment with sclerostin antibody (Scl-AbI) builds bone and can prevent or restore bone loss in a murine model of inflammatory bowel disease." (PMID 24432364, 2013). "In future studies, it may be informative to explore other tissues in the Sost−/− mice, as in a rat model of inflammatory bowel disease, which causes systemic inflammation, osteocytes that co-express SOST and TNFα are increased." (PMID 34502021, 2021). "Additionally, lower sclerostin levels, along with higher anti-sclerostin titers, predict the presence of axSpA in patients with inflammatory bowel disease (IBD)." (PMID 34948121, 2021).
mastocytosis (3 papers, 2020 to 2025). A clonal myeloproliferative neoplasm characterized by the proliferation and accumulation of neoplastic mast cells in one or multiple organs or organ systems. "The main aim of the study was to investigate whether neoplastic mast cells may be the source of sclerostin and whether there is an association between sclerostin and selected bone remodeling markers with mastocytosis related bone disease." (PMID 39747949, 2025). "It suggests the impact of sclerostin on the complex process of bone remodeling in patients with mastocytosis and justify the need for further research using an experimental bone formation model and larger patient groups." (PMID 39747949, 2025). "There are limited data available from in vitro studies and studies among patients with mastocytosis regarding the function of sclerostin in the pathogenesis of the disease." (PMID 39747949, 2025). "This would suggest the potential role of sclerostin and the Wnt pathway as one of the components of the pathomechanism of bone damage in mastocytosis." (PMID 39747949, 2025). "Sclerostin may serve as a marker of more advanced disease and bone disease in mastocytosis." (PMID 39747949, 2025). "Additionally, we observed significantly higher sclerostin concentrations in the plasma of patients with a diagnosis of ASM (both de novo and in progression), SM-AHN, and SSM compared to patients with less advanced mastocytosis: ISM and CM (34.2 vs. 19.3 [pmol/l])." (PMID 39747949, 2025).
Paget disease (3 papers, 2013 to 2024). A malignant neoplasm composed of large cells with large nuclei, prominent nucleoli, and abundant pale cytoplasm (Paget cells). "At least five papers report circulating levels of sclerostin in Paget’s disease patients, with two suggesting it is increased, while three found no change." (PMID 38457001, 2024). "Osteocytes, the most abundant cells in bone, are altered in Paget’s disease lesions, displaying increased size, decreased canalicular length, incomplete differentiation, and less sclerostin expression compared to controls in both patients and mouse models." (PMID 38457001, 2024). "The osteocytes in a bone biopsy from a patient with Paget’s disease showed reduced sclerostin staining compared to a control bone biopsy from a normal patient [23••]." (PMID 38457001, 2024). "Future experiments would assess local sclerostin expression by osteocytes within histological sections from pagetic patients’ bone lesions compared to controls to determine if osteocyte maturation is impaired or delayed in Paget’s disease." (PMID 38457001, 2024). "In future studies, pagetic bone samples from patients with Paget’s disease and from mouse models could be stained for osteocyte morphology and expression of RANKL, sclerostin and senescence markers and for IGF1 in osteoclasts." (PMID 38457001, 2024).
polycystic kidney disease (3 papers, 2017 to 2025). A usually autosomal dominant and less frequently autosomal recessive genetic disorder characterized by the presence of numerous cysts in the kidneys leading to end-stage renal failure. "Supporting this idea, in a genetic mouse model of polycystic kidney disease, Wnt/β-catenin pathway suppression was associated with high levels of both serum sclerostin and RANKL." (PMID 29808090, 2018). "Furthermore, in jck mouse, a genetic model of polycystic kidney disease that exhibits progressive renal disease, a transient increase in bone sclerostin was observed already in early stage disease." (PMID 28493902, 2017).
psoriasis (3 papers, 2019 to 2023). An autoimmune condition characterized by red, well-delineated plaques with silvery scales that are usually on the extensor surfaces and scalp. "An exploratory biomarker sub-study determines bone metabolism serum markers such as P1NP, CTX, RANKL, OPG, sclerostin, sThy-1 at baseline, week 16 and week 28 during treatment of 50 patients with psoriasis with secukinumab." (PMID 35812457, 2022). "Moreover, the study provided evidence for a positive correlation between sclerostin concentration and the duration of psoriasis." (PMID 37834893, 2023).
retinoblastoma (3 papers, 2022 to 2024). A malignant tumor that originates in the nuclear layer of the retina. "Knockdown of SOST has been shown to activate the Wnt/β-catenin signaling pathway to promote proliferation and invasion and decrease apoptosis in retinoblastoma cells." (PMID 38247829, 2024).
spondylitis (3 papers, 2012 to 2017). The inflammation of a vertebra. "This corresponds well with the previous finding that expression of Dkk1 and SOST was reduced in the spine of a proteoglycan-induced spondylitis (PGISp) mouse model of SpA, compared with controls." (PMID 28882159, 2017). "High SOST levels occur in hTNFtg mice, as TNF-α stimulates SOST expression but if the mice are treated with Dikkopf-1 neutralising antibodies, which also results in reduced levels of SOST, spondylitis occurs." (PMID 26612313, 2015). "Our data support this proposed elevated Wnt signalling in spondylitis with markedly decreased levels of the Wnt inhibitors DKK1 and SOST, the first such demonstration in a mouse model of SpA or AS." (PMID 23171658, 2012).
uremia (3 papers, 2018 to 2022). A clinical syndrome associated with the retention of renal waste products or uremic toxins in the blood. "It is believed that overexpression of sclerostin in bone cells because of uremia plays an important role in the low turnover of bone despite a high PTH concentration." (PMID 35220856, 2022). "Two possible mechanisms were discussed to explain this finding: one being the increased expression of sclerostin in uremia, the other being the decreased renal elimination (renal retention) of sclerostin in patients with a low glomerular filtration rate (GFR)." (PMID 34822428, 2021). "Therefore, even short-term uremia seems to lead to increased sclerostin expression." (PMID 34822428, 2021). "Interestingly, the increased circulating levels of the Wnt inhibitors sclerostin and Dkk1 have in uremia been suggested to be involved in the pathogenesis of the CKD-MBD, and a role of neutralizing antibodies against circulating Wnt-inhibitors has been proposed for treatment of CKD-MBD." (PMID 30075015, 2018). "In mice with advanced CKD, no relevant differences in bone changes in response to uremia were observed between sclerostin knock-out animals and wild-type controls." (PMID 34822428, 2021).
angina (2 papers, 2020 to 2022). "In addition, higher serum sclerostin levels were associated with higher PINP levels, lower CCS classes of angina, and a lower presence of multivessel disease." (PMID 31677125, 2020). "In addition, serum sclerostin levels were significantly associated with bone turnover markers, a lower presence of multivessel disease and a lower CCS angina class." (PMID 31677125, 2020).
anorexia nervosa (2 papers, 2020 to 2024). A disorder most often seen in adolescent females characterized by a refusal to maintain a minimally normal body weight, an intense fear of gaining weight, a disturbance in body image, and, in postmenarcheal females, the development of amenorrhea. "Longer‐term studies will be necessary to better understand the potential effects of estrogen on sclerostin and its potential benefits to bone mass in women with anorexia nervosa." (PMID 31956852, 2020). "Importantly, after 3 months, sclerostin levels rose again in our study, suggesting that the effects of estrogen on sclerostin may only be short‐lived in anorexia nervosa and that sclerostin may be able to escape the effects of estrogen." (PMID 31956852, 2020).
Ascites (2 papers, 2022 to 2023). Accumulation of fluid in the peritoneal cavity (between the layers of the peritoneum that lines the abdomen). "On the contrary, the relationship of sclerostin with android lean mass was statistically significant (ρ = 0.21; p = 0.037), even if patients with ascites were excluded (ρ = 0.23; p = 0.043)." (PMID 35807755, 2022). "We also observed a significant relationship between sclerostin and body mass index (ρ = 0.29; p = 0.005); this relationship persisted when only patients without ascites were included (ρ = 0.30; p = 0.013)." (PMID 35807755, 2022). "There was a significant relationship between sclerostin and trunk lean mass (ρ = 0.20 p = 0.044), a relationship that became non-significant if patients with ascites were excluded (ρ = 0.17; p = 0.12)." (PMID 35807755, 2022).
colitis (2 papers, 2022 to 2026). Inflammation of the colon. "Sost−/− mice exhibited increased intestinal Tph1 expression, while SKG mice showed reduced sclerostin and elevated Tph1 following curdlan-induced colitis-an effect dependent on the presence of intestinal microbiota." (PMID 41518441, 2026). "Sclerostin has been shown to play a pro-inflammatory role in arthritis and colitis." (PMID 35562828, 2022).
COVID-19 (2 papers, 2024 to 2025). A disease caused by infection with severe acute respiratory syndrome coronavirus 2. "Moderate intensity reactions against VEGF A, PlGF, and sclerostin were detected with the immunohistochemistry method in the placenta samples of patients who were diagnosed with COVID-19 during the 2nd trimester of pregnancy." (PMID 40943516, 2025). "Colostrum samples from mothers affected by COVID-19 showed elevated levels of sclerostin." (PMID 40943516, 2025). "Colostrum samples showed higher levels of OPG, SOST, and PTH in the COVID-19 group, a fact that could have noteworthy implications for energy metabolism, fetal skeletal development, and postnatal bone density and mineralization." (PMID 38610889, 2024).
Cushing syndrome (2 papers, 2019 to 2021). Cushing's syndrome (CS) encompasses a group of hormonal disorders caused by prolonged and high exposure levels to glucocorticoids that can be of either endogenous (adrenal cortex production) or exogenous (iatrogenic) origin. "Other studies report increased sclerostin levels after a longer period of GC treatment and in long-term supraphysiological levels of GC due to Cushing’s syndrome." (PMID 34229744, 2021).
Down syndrome (2 papers, 2018 to 2024). "As Wnt signaling is critical for atrioventricular canal formation, bone health, and pulmonary vascular homeostasis, we concluded that T21-mediated increased sclerostin levels would inappropriately inhibit Wnt activities and promote Down syndrome phenotypes." (PMID 38828726, 2024).
endothelial dysfunction (2 papers, 2021 to 2025). In vascular diseases, endothelial dysfunction is a systemic pathological state of the endothelium (the inner lining of blood vessels) and can be broadly defined as an imbalance between vasodilating and vasoconstricting substances produced by (or acting on) the endothelium. "The most common findings include endothelial dysfunction with thrombosis, chorangiosis, villous edema, and fibrinoid necrosis, as well as the increased expression of sclerostin and Annexin A2." (PMID 40943516, 2025). "In the intima, Wnt signaling is involved in endothelial dysfunction, macrophage recruitment, and activation, and sclerostin was observed to downregulate the expression of matrix metalloproteinase 9, OPG, and osteopontin genes." (PMID 33923139, 2021).
haemophilia (2 papers, 2022 to 2023). "Here, the levels of sclerostin even correlated with the severity of the disease, with patients with severe hemophilia having lower sclerostin concentrations than those with mild or moderate disease." (PMID 35186990, 2022). "This stands in contrast to data from adult patients with hemophilia, in which lower serum sclerostin and Dkk-1 levels were found." (PMID 35186990, 2022).
Hypercalcemia (2 papers, 2014 to 2022). An abnormally increased calcium concentration in the blood. "However, in contrast to HYPVE mice, WT-SPR4 mice had reduced osteocalcin and sclerostin with markedly increased 1.25(OH)2D3 and hypercalcemia." (PMID 24839967, 2014). "Thus with WT mice treated with SPR4-peptide (binds to and inactivates ASARM-motif and peptide), the dramatic increase in 1.25(OH)2D3, hypercalcemia and reduced sclerostin may have helped to counteract the reduced osteocalcin resulting in normal glucose and insulin levels." (PMID 24839967, 2014).
Hyperinsulinemia (2 papers, 2023 to 2024). An increased concentration of insulin in the blood. "Insulin sensitivity was inversely associated with serum sclerostin in obese women; hyperinsulinemia did not affect serum sclerostin in both lean and obese women." (PMID 37569816, 2023). "Although patients with T1DM and T2DM with a distinct pathophysiology were associated with a higher expression of Wnt inhibitors, hyperinsulinemia did not affect the serum sclerostin level." (PMID 37569816, 2023).
ischaemic stroke (2 papers, 2022 to 2024). "Sclerostin-targeted drugs, SERMs, and oral calcium supplements have been associated with certain CVD risks such as MI and ischemic stroke." (PMID 35573562, 2022). "Our study does not show any association between sclerostin levels and ischaemic stroke." (PMID 39537602, 2024).